INS (insulin)
Diseases named in the same sentence as INS in open-access papers (continued):
Sharing a sentence is not in itself a finding about the gene and the disease.
diabetes (continued). "As noted by others, we observed an independent association between maternal BMI and cord blood insulin which may reflect a role for subclinical insulin resistance in overweight or obese individuals that have not been diagnosed with diabetes." (PMID 35197933, 2022). "This is relevant given that kisspeptin administration has been observed to enhance glucose‐stimulated insulin secretion in healthy men, indicating that kisspeptin may modulate both reproductive hormone secretion and insulin release in patients with diabetes with further clinical studies warranted." (PMID 36262016, 2022). "The lists of foods generated in this study may be used to fill the gap in knowledge of the diets for the group reporting taking insulin or diabetic patients among U.S. adults, specifically, menus and dietary interventions developed to improve diabetes management may be informed by the lists." (PMID 36014790, 2022). "The intensive education program structured in four sessions on insulin administration, blood glucose management, nutrition, and physical exercise with a patient-centered motivational methodology demonstrated effectiveness on patients’ diabetes knowledge, emotional regulation, and self-care." (PMID 36498437, 2022). "Diabetes mellitus (DM) is a chronic metabolic syndrome, which is mainly characterized by insufficient insulin secretion or functional impairment, resulting in long-term hyperglycemia and chronic inflammation." (PMID 36009510, 2022). "Diabetes mellitus (DM) is a complicated metabolic illness that is characterized by the destruction of insulin-secreting β-cells or by insulin resistance, whereby the insulin-target organs are unresponsive to insulin action." (PMID 35458586, 2022). "Diabetes Mellitus (DM) is a metabolic disorder characterized by the presence of hyperglycemia due to defects in insulin secretion, insulin action, or both." (PMID 35323407, 2022). "We surmise that the nonstandard insulin therapy that results in FPG fluctuation might be associated with the short‐term poor prognosis of diabetes patients." (PMID 36069119, 2022). "In 2002, the first Drosophila Diabetes model was established, and the removal of insulin-producing cells (IPCs) in the fruit fly brain could produce phenotypes that were similar to that of human type 1 diabetes, including elevated blood glucose level, weight loss, and developmental delay." (PMID 36035393, 2022). "However, further improvement in CGM accuracy, particularly in the hypoglycemic range, is crucial for the development of reliable diabetes technology, especially for automated insulin delivery systems, as well as for reducing the burden of diabetes management for PLWD." (PMID 35200366, 2022). "Diabetes mellitus (DM) is a chronic metabolic disorder characterized by the presence of hyperglycemia due to an impairment of insulin secretion, defective insulin action, or both." (PMID 35457686, 2022). "Indeed, the used diabetes devices intended for one-time use (injection needles, syringes, lancets, strips, blood glucose monitors, sensors, insulin bottles, infusion tubing, disposable pumps, device batteries, packaging, etc.)generate a great quantity of garbage." (PMID 36497884, 2022). "However, adherence to insulin therapy and associated factors among diabetic mellitus (DM) patients are still not studied adequately in Ethiopia." (PMID 35704654, 2022). "Metabolic surgery improves insulin secretion and sensitivity in patients with T2D, but the effect on patients with normal glucose tolerance or prediabetes (pre-DM) needs further understanding." (PMID 36422274, 2022). "Mujumdar and Vaidehi suggested a diabetes prediction model for accurate diagnosis of diabetes that contains a few additional factors that are involved for diabetes in addition to standard indicators such as blood glucose, body mass index (BMI), age, insulin, and so on." (PMID 35372240, 2022).
diabetes (continued). "However, the newspaper articles did report the essential role of insulin for diabetes treatment and introduced readers to new dosage forms and novel insulin analogues that minimise the risk of hypoglycaemia." (PMID 36243730, 2022). "Injections of insulin plus the usage of oral hypoglycemic medications make up the standard treatment for diabetes mellitus (DM)." (PMID 35965680, 2022). "For the patients with severe diabetes, when oral hypoglycemic drugs failed and the duration of diabetes gradually increased (more than 10-15 years), patients with type 2 diabetes needed to inject insulin to control blood glucose because the function of pancreatic beta cells was gradually depleted." (PMID 35436905, 2022). "This could be because insulin production in patients with T2DM is impaired due to progressive decline or deterioration of the beta-cell function of the pancreas which eventually dictates that these patients require insulin injection to control their diabetes or to keep normoglycemia." (PMID 35854336, 2022). "Diabetes mellitus (DM) is characterized by chronic hyperglycemia originating from the disturbance in either insulin release or action or both." (PMID 36248064, 2022). "While effective at elevating plasma insulin and lowering glycated hemoglobin A1c, sulfonylureas are not protective to the β-cell and, in fact, may accelerate β-cell demise and progression to overt diabetes." (PMID 35204835, 2022). "Higher serum OCN level is closely related to better blood glucose control, higher insulin sensitivity, increased early-phase insulin secretion of islet β cells and appropriate inhibition of postprandial glucagon secretion of islet ɑ cells in adult patients with type 2 diabetes mellitus." (PMID 36307866, 2022). "The evaluation of a clinical decision tool for non-diabetes specialists for the management of raised glucose saw a reduction in the percentage of patients with hyperglycaemia as their primary reason for admission who then received an intravenous insulin infusion (84% to 56% (P<0.01)." (PMID 36992734, 2022). "Diabetes mellitus (DM) is characterised by a high glucose level in the blood (hyperglycaemia) resulting from defective mechanisms in insulin secretion, insulin action, or both." (PMID 35089931, 2022). "When asked to identify the top three research objectives, the majority of respondents with T1DM selected ‘diabetes complications are detected early or, better yet, prevented’ (32.9%) and ‘technical systems think and act independently when measuring blood sugar and injecting insulin’ (32.9%)." (PMID 36460748, 2022). "Diabetes mellitus (DM) is a complex group of diseases characterized by high blood glucose levels due to either an inability to produce insulin or an insensitivity to insulin." (PMID 34269526, 2022). "Diabetes mellitus is a chronic metabolic disease that is characterized by elevation of the plasma glucose levels (hyperglycemic) as a result of impairment of glucose utilization secondary to insufficient insulin secretion or insensitivity of insulin in the peripheral tissues." (PMID 36619200, 2022). "Mechanistically, VD–CAL regulates from the organs to the blood, influencing insulin, lipids, hormone, cell, and inflammatory functions in obesity and its comorbidities, such as non-alcoholic fatty liver disease, cardiovascular disease, and type-2 diabetes mellitus." (PMID 35956362, 2022). "For instance, C-peptide might exert an insulin-independent effect on bone mass and a lower level of C-peptide meant a higher risk of osteoporosis in postmenopausal women without diabetes." (PMID 36192784, 2022). "Diabetes Mellitus (DM) is characterized by hyperglycemia as a result of an absolute or relative deficit in insulin production or action." (PMID 35444994, 2022).
diabetes (continued). "Most notably, the cause of IR in obesity and type 2 diabetes mellitus involves the complex interplay of multiple metabolic pathways, which is closely related with excessive specific lipids (including FFA) accumulation resulting in damage of insulin synthesis, secretion, and signal transduction." (PMID 35154697, 2022). "Finally, many metabolites and signaling pathways, which improve insulin secretion, could be targeted to treat diabetes but further investigations are required to propose the best therapy." (PMID 35185804, 2022). "This may be of extreme importance when considering diabetes behavior management, as it may assist individuals with T1DM to adhere to diabetes care plans, for example by resisting the urge to eat when glycemia is high and administering insulin at the correct times." (PMID 36992790, 2022). "Diabetes mellitus (DM) is a group of endocrine and metabolic disorders, characterized by hyperglycemia due to insufficient insulin secretion or insulin action." (PMID 35480084, 2022). "For example, children with diabetes may show specific resistance to wearing an insulin pump." (PMID 36141360, 2022). "In addition, research about diabetes mice has revealed that Myr can regulate insulin sensitivity, glucose tolerance, mitochondrial function and blood glucose level of obese mice, indicating that Myr can relieve the pathology of diabetes and its complications by reducing blood glucose level." (PMID 36296589, 2022). "A key factor may be the relationship between diabetes, insulin, and zinc, which is complex with no apparent cause and effect relationships." (PMID 35682762, 2022). "Diabetes mellitus (DM) comprises a group of metabolic ailments characterized by hyperglycemia arising from alterations in the secretion and/or activity of insulin." (PMID 36405233, 2022). "Therefore, when injectable therapy is needed, most clinical practice recommendations, including the very recent American Diabetes Association guideline in 2022, suggest GLP-1 RA is preferred to insulin based on its additional benefits in body weight and organ protection." (PMID 36559020, 2022). "Diabetes mellitus is a nearly constant finding of WS: it is usually insulin-dependent, non-autoimmune, non-HLA-linked diabetes and, unlike type 1 diabetes mellitus, it is characterized by rare microvascular complications and a decreased tendency to develop ketoacidosis." (PMID 35055657, 2022). "Diabetes mellitus (DM) is a metabolic syndrome characterized by impaired insulin secretion, insulin sensitivity, or both." (PMID 36552528, 2022). "However, a new source of insulin-producing cells could enable the widespread use of cell therapy for diabetes treatment." (PMID 36090777, 2022). "In C. cassia, the main A-type PAC oligomers could reverse palmitic acid-induced dysfunction of glucose-stimulated insulin secretion in primary cultured islets, improved the insulin concentration in the blood and pancreas, and (as C. japonica) improved insulin sensitivity in type 2 diabetes mellitus." (PMID 36500445, 2022). "Diabetes mellitus (DM) is a chronic hyperglycemic (HG) disorder resulting from an impaired carbohydrate metabolism like insufficient insulin secretion, its action, or both." (PMID 35794254, 2022). "Therefore, insulin substrate proteins are an important target for treating diabetes." (PMID 36479195, 2022). "However, obesity decreases insulin sensitivity in dogs, and it is possible that it may also reduce the control of diabetes." (PMID 36262532, 2022). "Here, we have successfully demonstrated an integrated closed-loop diabetes management system that consists of a microtube-type biosensor implanted into the subcutaneous tissue to detect glucose, an electroosmotic micropump to inject insulin, and a PCB to achieve the control algorithm." (PMID 36349339, 2022).
diabetes (continued). "Because insulin sensitizers offer so many treatment advantages, finding new examples of these drugs in natural compounds may play a major role in improving the quality of life of patients with diabetes." (PMID 35502441, 2022). "We surmised that non-obese patients with PA may have a higher risk of diabetes than EH patients due to increased insulin resistance from high aldosterone." (PMID 36045354, 2022). "Diabetes mellitus (DM) is a metabolic disorder manifested by chronic hyperglycemia with potentially severe effects on insulin sensitivity and secretion." (PMID 35929593, 2022). "Coupled with these examples, we observed that DM-SSP-associated DMLs were enriched at genes implicated in the immune response, insulin signaling, glucose and lipid metabolism, and cardiometabolic disease, including type 2 diabetes mellitus." (PMID 35851422, 2022). "Polymorphisms in the CDKAL1 gene are reported to be associated with type 2 diabetes mellitus in several human populations, and the CDKAL1 gene is involved in the metabolism of insulin that affects glucose mediated mechanisms, crucial for feed-efficiency and other growth and adaptation traits." (PMID 36353101, 2022). "Furthermore, it is likely that insulin use may differentiate food and beverage choice and intake among those reporting diabetes, as dietary attention to manage blood glucose levels is necessary for insulin treatment." (PMID 36014790, 2022). "In Mexico, Diabetes mellitus (DM) is a serious health problem, and although the current pharmacological treatments for DM such as insulin and oral hypoglycemics are available, the Mexican population continues to use medicinal plants in the treatment of DM." (PMID 35684376, 2022). "Therefore, the long-term use of insulin to control blood sugar may weaken the gastric-emptying function of patients with diabetes, aggravating the symptoms of gastroparesis." (PMID 36482537, 2022). "Diabetes mellitus (DM) is a group of metabolic disorders characterized by a chronic hyperglycemic condition resulting from defects in insulin secretion, insulin action, or both." (PMID 35888080, 2022). "DM is a complex chronic metabolic disease associated with type 1 diabetes (T1DM; juvenile-onset diabetes mellitus and insufficient insulin production) and type 2 diabetes (T2DM; insulin resistance)." (PMID 35053962, 2022). "Therefore, insulin plays a role in the pathophysiology of diabetes-related cognitive decline." (PMID 36225477, 2022). "Diabetes-specific autoimmunity, assessed by the titration of at least two autoantibodies against glutamic acid decarboxylase 65 autoantibodies, tyrosine phosphatase-like insulinoma antigen 2, insulin, and β-cell-specific zinc transporter 8 autoantibodies, was absent in all cases." (PMID 35010780, 2022). "This is of major concern, as Black people born in sub-Saharan African countries may be at greater risk of developing diabetes at a lean-to-normal BMI and have β-cell-failure or secretory dysfunction, rather than peripheral insulin resistance." (PMID 36211668, 2022). "They found that at least four different genetic factors or VDR modifications may have a role in the development of type 2 diabetes mellitus: alteration of calcium metabolism, modification of adipocyte activity, modification of insulin secretion, and modification of cytokine production." (PMID 36407246, 2022). "However, the patients who had diabetes mellitus may have had a mild condition, and few were taking medication or insulin injections." (PMID 35520293, 2022). "However, in long-term weight loss dietary interventions, individuals with non-diabetes, overweight and obese, and rs12255372 risk genotype had greater decreases in glucose and insulin concentrations per unit reduction in BMI compared to the non-risk allele." (PMID 36155628, 2022). "All patients had comorbidities that included essential hypertension (HTN), diabetes mellitus (DM, insulin-dependent or insulin-resistant), and obesity (BMI 33.08–34.8 kg/m2)." (PMID 35237625, 2022).
diabetes (continued). "Moreover, whether long-term consumption of diet-induced insulin secretion is associated with chronic diseases such as CVD and type 2 diabetes mellitus remain controversial in the general population." (PMID 36585722, 2022). "Guanidine derivatives were used to treat diabetes mellitus (DM) in the 1920s and 1930s but with the availability of insulin were discontinued due to their toxicity." (PMID 35631452, 2022). "Further, one could speculate whether the association is attenuated also by grouping patients with newly detected glucose perturbations with those with known diabetes, as the latter might be treated with drugs affecting mannose levels and/or insulin sensitivity." (PMID 36151569, 2022). "Diabetes mellitus (DM) is a chronic metabolic abnormality of glucose metabolism due to insufficient insulin or insulin resistance, characterized by high blood glucose levels." (PMID 36350840, 2022). "In addition, the subjects with macro-albuminuria had significantly oldest age, longest diabetes duration, lowest eGFR, highest prevalence of hypertension, lowest target attainment rate of blood pressure, highest rate of insulin and anti-hypertensive drugs treatment." (PMID 36550864, 2022). "Modification of the F-actin network is key to islet cell function as it mediates insulin secretion and results here suggest that DSG2 is protective with loss of DSG2 in the Beta-TC-6 cells increasing the release of TNFα, a known pathogenic and proinflammatory cytokine implicated in diabetes." (PMID 36309486, 2022). "Diabetes mellitus (DM) is a complicated metabolic disorder featured by hyperglycemia that results from defects in insulin secretion and insulin action and is related to alterations in protein, fat, and carbohydrate metabolism." (PMID 36127704, 2022). "Diabetes mellitus (DM) is a slow damaging disease known worldwide due to the low insulin production or created damaged insulin that is unusable for body cells." (PMID 35197753, 2022). "In SSA, Human herpesvirus 8 infection is not related to a decrease in insulin sensitivity in patients with diabetes, but rather is associated with low insulin secretion, which is supported by an early in vitro study showing that Human herpesvirus 8 can directly infect human pancreatic beta cells." (PMID 36166072, 2022). "T1DM affects roughly 5–10% of all diabetes patients and is characterized by the death of pancreatic insulin-producing β-cells destroyed by the immune system, resulting in an extreme shortage of insulin, hyperglycemia, inflammation, oxidative damages and other metabolic problems." (PMID 36297746, 2022). "Diabetes mellitus (DM) is a group of metabolic diseases marked by chronic hyperglycemia arising from defects in insulin secretion or resistance to insulin action, or both, with associated abnormalities in carbohydrate, protein, and lipid metabolism." (PMID 36225474, 2022). "Overcoming clinical inertia by early initiation of a combination therapy or insulin therapy could help in achieving glycaemic targets faster in people who are poorly controlled on monotherapy and thus alleviate the burden of diabetes‐related vascular complications." (PMID 34856077, 2022). "Few reported having discussed their diabetes management with the nursing/midwifery staff whilst in hospital (n = 47, 32.6%) or thought the nurses and midwives had a good understanding of different types of insulin (n = 43, 30.1%) and their administration (n = 47, 33.3%)." (PMID 36068537, 2022). "In this study, we report that a CAER platform using autologous ERs as INS-carriers and GOx expressed on the surface of the cells to function as a glucose-activated switch could accomplish glycemic control and hemodialysis for diabetes mellitus therapy." (PMID 36296745, 2022).